SCN1A (sodium voltage-gated channel alpha subunit 1)
Diseases named in the same sentence as SCN1A in open-access papers (continued):
Sharing a sentence is not in itself a finding about the gene and the disease.
epilepsy (continued). "In particular, zebrafish mutants of scn1lab have been used as a model of Dravet syndrome, a severe, intractable form of epilepsy, which in most cases is caused by mutations in SCN1A." (PMID 30210288, 2018). "Mutant larvae of scn1lab, an ortholog of the ASD- and epilepsy-associated genes, SCN1A and SCN2A, exhibit spontaneous seizures (discussed in the “Epilepsy” section), as well as nighttime hyperactivity and increased thigmotaxis." (PMID 30210288, 2018). "SCN1A rs3812718 polymorphism has been attributed to be a possible modifying factor for epilepsy therapeutics, particularly in the Asian populations." (PMID 30413604, 2018). "Heterologous expression systems, in which cloned sodium channel α-subunits are expressed in an intrinsically non-excitable cell, were the first models used to investigate the cellular consequences of SCN1A mutations associated with epilepsy." (PMID 28082152, 2018). "One example is the human SCN1A sodium channel gene, which has more than 600 possible mutations which can confer a wide spectrum of epilepsies." (PMID 29997502, 2018). "A study in Han Chinese people with epilepsy found an association between the effects of SCN1A, ABCC2 and UGT2B7 genetic polymorphisms and oxcarbazepine maintenance doses." (PMID 28082152, 2018). "For instance, mutations in the SCN1A gene, encoding voltage-gated sodium channels, cause a selective decrease in excitability of GABAergic interneurons that lead to the severe epilepsy of Dravet syndrome." (PMID 29377906, 2018). "An SCN1A mutation was first discovered in epilepsy in 2000, and now hundreds of new SCN1A mutations have been described in epilepsy patients, making it the most common epilepsy-related gene." (PMID 30185235, 2018). "Although it can be used for treating several epilepsies and seizures, its association with the SCN1A rs3812718 polymorphism remained unclear." (PMID 30413604, 2018). "Loss-of-function mutations in SCN1A cause Dravet syndrome (DS), a catastrophic childhood epilepsy in which patients experience comorbid behavioral conditions, including movement disorders, sleep abnormalities, anxiety, and intellectual disability." (PMID 28812061, 2017). "Increased INaP is associated with mutations in SCN1A that have been identified from individuals with epilepsy and is specifically reduced by AEDs such as phenytoin, valproate and lamotrigine." (PMID 28067623, 2017). "For example, approximately 700 pathogenic CDS variants have been reported in the epilepsy-associated gene SCN1A." (PMID 28558813, 2017). "We chose to restrict our study to epilepsy patients carrying a truncation mutation in SCN1A to control for the effect of ‘mutation type’ on clinical outcome." (PMID 28686619, 2017). "The alternative splicing of exon 5 of the epilepsy-associated gene SCN1A generates isoforms of the voltage-gated sodium channel that differ in their sensitivity to the anti-epileptic medications phenytoin and lamotrigine." (PMID 28558813, 2017). "SCN1A mutations result in a wide spectrum of epilepsy phenotypes ranging from simple febrile seizures to Dravet syndrome, a severe epileptic encephalopathy." (PMID 28490751, 2017). "We analyzed sequence data of 448 epilepsy patients and 734 controls for SCN1A variants previously reported as disease causing collected by the HGMD." (PMID 26990884, 2016). "Although SCN1A de novo mutations seem to be specific to epilepsy, we observe SCN2A de novo mutations in both ASD and ID, which suggests that long-term potentiation has a role in multiple forms of ND." (PMID 26917491, 2016). "We investigated if there were genetic variants in 3’UTR of SCN1A, affecting the microRNA-mRNA 3’UTR interaction and SCN1A gene repression, potentially associated with epilepsy." (PMID 27473590, 2016). "In around 88% of epilepsy patients carrying rare SCN1A mutations, these arise de novo, whereas only 12% of the affected individuals inherit the mutation from a, usually unaffected, parent." (PMID 26990884, 2016).
epilepsy (continued). "One of the first ion channel “epilepsy” genes identified was SCN1A, which encodes the neuronal voltage-gated sodium channel NaV1.1." (PMID 27582020, 2016). "For example, zebrafish have two similar homologs of the human SCN1A gene, scn1laa and scn1lab; both genes are expressed in the brain and homozygous loss-of-function mutation in scn1lab results in epilepsy and serves as a model for Dravet syndrome." (PMID 26963117, 2016). "Mutations in SCN1A, the gene encoding the α subunit of Nav1.1 channel, can cause epilepsies with wide ranges of clinical phenotypes, which are associated with the contrasting effects of channel loss-of-function or gain-of-function." (PMID 26731440, 2016). "In this project, CRISPR/Cas9- and TALEN-mediated genome-editing techniques were applied to induced pluripotent stem cell (iPSC)-based-disease model to explore the mechanism of epilepsy caused by SCN1A loss-of-function mutation." (PMID 26731440, 2016). "Since mutations in SCN1A, the major gene implicated in epilepsy, are found in the majority of Dravet syndrome (DS) patients, we focused on missed SCN1A mutations." (PMID 27465585, 2016). "Our results highlight key genes for brain development including drawing attention to SCN1A mutations in adults with early-onset pharmacoresistant epilepsy and ID." (PMID 27113213, 2016). "A constituent gene within M30 is SCN1A, which is a known genome-wide significant susceptibility gene for epilepsy." (PMID 27955713, 2016). "The mutations in the coding region of voltage-gated sodium channel alpha 1 subunit gene, SCN1A, were identified in epileptic patients and confirmed as causative factors of epilepsy." (PMID 27473590, 2016). "Using this system, we investigated the epilepsy caused by SCN1A loss-of-function mutation on the Nav1.1-expressing neuronal subtype as well as the whole neuronal network." (PMID 26731440, 2016). "We therefore re-tested the enrichment of association between M30 and epilepsy after excluding SCN1A from the list of M30 genes." (PMID 27955713, 2016). "The presence of the SCN1A IVS5-91G>A variant allele is associated with increased epilepsy susceptibility." (PMID 26555147, 2015). "In our previous cross-sectional study of patients with epilepsy, the SCN1A A/A genotype was also associated with CBZ-resistant epilepsy, including in patients co-administered VPA." (PMID 26484865, 2015). "Dravet’s syndrome (DS) is a form of autism and epilepsy in which there is a SCN1A mutation that encodes for VGSC type-1 (NaV1.1), the primary sodium channel in the GABAergic interneurons." (PMID 25592685, 2015). "DS is characterized by comorbidity of epilepsy and psychiatric disorders, and linked to Nav1.1(SCN1A) channel dysfunction." (PMID 25784856, 2015). "One specific epilepsy disorder that has increased risk of sudden death, Dravet Syndrome, is caused by mutations in the Na+ channel SCN1A, which is expressed both in the heart and the brain." (PMID 25713300, 2015). "Our study has three key findings: (i) the SCN1A IVS5-91G>A SNP is associated with susceptibility to epilepsy, (ii) SNPs in EPHX1 gene influence CBZ pharmacokinetic and (iii) CBZ plasma level is not an indicator of resistance to the therapy." (PMID 26555147, 2015). "In the whole cohort consisting of all epilepsy, the region of the sodium channel subunit gene SCN1A was clearly associated with the disease." (PMID 25087078, 2014). "For example, mutations in SCN1A have been reported to cause epilepsy with the symptoms ranging from febrile seizures and GEFS+ to SMEI, and mutations in SCN2A are identified to cause BFNIS, GEFS+, SMEI, and intractable epilepsy with mental decline." (PMID 23662118, 2013). "Test for epilepsy syndromes associated with mutations in the SCN1A gene including the severe infantile onset epilepsies- typical Dravet syndrome (severe myoclonic epilepsy in infancy) and its borderline subtypes." (PMID 23653348, 2013).
epilepsy (continued). "Several rarer epilepsies featuring febrile seizures are caused by mutations in SCN1A, which encodes a brain-expressed sodium channel subunit targeted by many anti-epileptic drugs." (PMID 24014518, 2013). "The aim of this study was to analyze the neuropsychological and behavioral features prospectively in a large cohort of patients with DS and its relation with SCN1A mutation and the characteristics of epilepsy." (PMID 24225340, 2013). "Our objective was to prospectively analyze the neuropsychological features in a large cohort of DS patients and its relationships with epilepsy and SCN1A mutation." (PMID 24225340, 2013). "SCN1A, however, emerges as the most plausible candidate, due both to its proximity to the associated region and its role in other epilepsies with febrile seizures." (PMID 24014518, 2013). "Familial missense mutations in scn1a have been linked to epilepsy, migraines and brain structure in aging individuals." (PMID 23597049, 2013). "Association of SCN1A mutation in epilepsy patients with evolving autistic features is an interesting topic for future clinical research." (PMID 22848613, 2012). "SCN1A is regarded as the most important epilepsy gene associated with a spectrum of epilepsy syndromes ranging from milder phenotypes in generalized epilepsy with febrile seizures plus (GEFS+) to severe myoclonic epilepsy of infancy (Dravet syndrome)." (PMID 22848613, 2012). "In the present study, SCN1A mutation analysis was performed in 100 patients recruited from the Epilepsy Clinic of Queen Mary Hospital and Duchess of Kent Children’s Hospital, being affiliated hospitals of the University of Hong Kong." (PMID 22848613, 2012). "SCN1A encodes the α1 subunit of neuronal NaV1.1 voltage-gated sodium channels and is a well-known epilepsy gene harbouring over 100 truncating and missense mutations associated with childhood epilepsy (i.e. severe myoclonic epilepsy of infancy)." (PMID 22940869, 2012). "Even though SCN1A c.3184 A>G polymorphism was associated with generalized epilepsy, it showed no influence on the multidrug resistance phenotype in patients with epilepsy." (PMID 21747585, 2011). "The development of protocols for more efficient and reliable molecular diagnostics would allow a wider appreciation of the role of the SCN1A gene and of other genes encoding for ion channels in different epilepsies and epilepsy syndromes." (PMID 21713554, 2011). "This study provides evidence for a role of SCN9A in human epilepsies, both as a cause of FS and as a partner with SCN1A mutations." (PMID 19763161, 2009). "SCN1A is also clinically very relevant as it contributes to the largest number of mutations linked with epilepsy." (PMID 19099596, 2008). "Similarly, genomic profiling has detected monogenic causes of epilepsy, such as SCN1A mutations in Dravet syndrome, which lead to precise molecular diagnoses and treatment plans." (PMID 40806492, 2025). "The reason for this is that SCN1A seizure disorder is inherited in an autosomal dominant manner, so probands with SCN1A seizure disorder may have hereditary or de novo pathogenic variants." (PMID 40003892, 2025). "Since then, the field of genomics has opened the door to understanding the genetic disposition to many neurologic diseases, including studying IDH mutations in gliomas and IDH1 mutations in glioblastomas, as well as understanding SCN1A mutations associated with epilepsy." (PMID 40806492, 2025). "Some SCN1A mutations linked to epilepsy can lead to channel dysfunction." (PMID 40394709, 2025). "In certain epilepsy types, the genetic cause is well known, like SCN1A mutation in Dravet syndrome." (PMID 40529445, 2025). "The association between familial hemiplegic migraine-related genes (CACNA1A, ATP1A2, and SCN1A) and both migraine and epilepsy, as well as the impact of polymorphisms in pain-related sodium channels SCN9A and SCN10A on migraine chronification, have been further elucidated." (PMID 41404467, 2025).
epilepsy (continued). "Other hand, Dravet syndrome of severe epilepsies is almost caused by SCN1A mutation." (PMID 40003892, 2025). "In addition to epilepsy, SCN1A variants are also associated with other disorders, including familial hemiplegic migraine (FHM) and autism spectrum disorders (ASD)." (PMID 40217529, 2024). "The intricate connection between SST+ interneurons and seizures goes beyond a simple association, exemplified by a decrease in SST+ interneuron activity in the neocortex observed in Dravet syndrome, an example of a monogenic epilepsy caused by a pathogenic variant in the SCN1A gene." (PMID 38714540, 2024). "In the present study, we systematically reviewed SCN1A mutations associated with epilepsy and analyzed the spatial and frequency distributions, aiming to provide an important insight into the mutagenesis etiopathology of SCN1A-associated epilepsy." (PMID 40217529, 2024). "The SCN1A gene stands as the foremost and most prevalent gene associated with epilepsy." (PMID 40217529, 2024). "Loss of function SCN1A mutations are associated with a broad spectrum of phenotypes in people that vary in severity, from ‘just’ febrile seizures, or epilepsy with febrile seizures plus (GEFS+), which are both relatively milder, to Dravet syndrome, the most severe." (PMID 37594756, 2024). "Overall, it may be surprising to some people within the epilepsy field that a metabolic therapy has efficacy in Dravet syndrome, considering that the primary cause of this epilepsy is genetic loss of function of SCN1A." (PMID 37594756, 2024). "This review summarises metabolic changes that have been found in people with epilepsy and in rodent seizure and epilepsy models, what is currently known about metabolism in specific epilepsies associated with mutations in SCN1A and KCNA1, and alterations found after ketogenic diet treatment." (PMID 37594756, 2024). "Among the nine α-subunit-coding genes, variants in sodium voltage-gated channel alpha subunit type 1 (SCN1A, which encodes NaV1.1) have been reported to be associated with several human neurological disorders, such as autism spectrum disorder, epilepsy and hemiplegic migraine." (PMID 39258309, 2024). "It has been reported that the polymorphism of the SCN1A gene may play a role in the response to anti-epileptic drugs in patients with drug-resistant epilepsy, which is of great significance for clinical practice." (PMID 38628642, 2024). "Mutations in SCN1A have been associated with various seizure disorders and epilepsy syndromes." (PMID 39024300, 2024). "Variants detected in epilepsy-related genes (DEPDC5, CHD2, SCN8A and IQSEC2) have been reported in patients with SCN1A variants and were considered to contribute to blended phenotypes comprising features of the disorder associated with the epilepsy gene and Dravet syndrome." (PMID 38891831, 2024). "In particular, pathogenic variants in the SCN1A gene have been correlated with a wide spectrum of epilepsy phenotypes, including genetic epilepsy with febrile seizures, Dravet Syndrome, developmental and epileptic encephalopathies, and epilepsy of infancy with migrating focal seizures." (PMID 39336815, 2024). "Furthermore, another Chinese epilepsy cohort study demonstrated associations between SCN1A rs3812718 and SCN2A rs2304016 with VPA response." (PMID 38837984, 2024). "SCN1A is the most well-recognized and commonly mutated gene related to epilepsy." (PMID 40217529, 2024). "SCN1A was first associated with epilepsy when a missense mutation was identified in affected members of two families possessing a strong lineage of generalized convulsions and febrile seizures consistent with the clinical syndrome of Genetic Epilepsy with Febrile Seizure Plus (GEFS+)." (PMID 37139072, 2023). "SCN1A encodes the alpha subunit of the voltage-gated sodium channel, NaV1.1, and is the gene most strongly associated with epilepsy, implicated in both rare monogenic syndromes and common forms of epilepsy with complex inheritance." (PMID 37139072, 2023).
epilepsy (continued). "SCN1A is among the genes most frequently associated with epilepsy and genetic encephalopathies, and it might contribute to age-related cognitive decline." (PMID 37819378, 2023). "Interestingly, we find that the only epilepsy variant in our data that also associates with migraine is rs59237858 in SCN1A, the gene that encodes Nav1.1." (PMID 37884687, 2023). "Among the genetic-idiopathic epilepsies in which VGSCs are implicated, Dravet syndrome (also known as SMEI) is a type of highly debilitating, recalcitrant and pharmacoresistant epilepsy resulted from missense mutations in the VGSC protein NaV1.1 encoded by the SCN1A gene." (PMID 40217485, 2023). "The most common monogenic cause of epilepsy is SCN1A variants." (PMID 38025388, 2023). "In rare cases, heterozygous SCN1A mutations might cause myoclonic-atonic epilepsy or epilepsy of infancy with migrating seizures." (PMID 35414300, 2023). "FHM3 is caused by mutations in SCN1A and constitutes a severe subtype of migraine with aura, characterized by some degrees of hemiparesis, sometimes associated with other neurological symptoms, such as epilepsy or blindness." (PMID 37240836, 2023). "Both gain-of-function (GOF) and loss-of-function (LOF) effects could be responsible for SCN1A-associated epilepsies." (PMID 37576022, 2023). "Finally, diagnostic findings in patients with syndromic vs. non-syndromic symptoms revealed a significant overlap of frequent causes of monogenic epilepsies, including SCN1A, CACNA1A, and SETD1B, confirming the heterogeneity of the associated conditions." (PMID 38125836, 2023). "This is particularly relevant in epilepsy due to the heterogeneous nature of genetic epilepsies, with more than 500 loci listed as potentially causative when mutated and in some cases, such as in SCN1A-related epilepsies, over 1,250 distinct mutations identified in patients." (PMID 37719765, 2023). "Polymorphisms of the SCN1A gene could play a role in the response to antiseizure medications in patients with drug-resistant epilepsy in developmental age, with key implications for clinical practice." (PMID 37470002, 2023). "However, recent studies have identified SCN1A gain-of-function variants associated with epilepsy, and the presence of cellular and synaptic changes in mouse models that point toward homeostatic adaptations and complex network remodeling." (PMID 37139072, 2023). "SCN1A GOF-mutant-associated epilepsy may be controlled by the appropriate use of adequate AEDs that can inhibit sodium channels, such as phenytoin and carbamazepine." (PMID 38203200, 2023). "Notably, Scn1a is a super culprit gene with over 1000 associated disease-causing mutations, most of which are linked to different forms of epilepsy." (PMID 36278870, 2022). "In conclusion, within (SCN1A) gene the rs3812718, rs10194956, rs13383628, rs6432861 and rs1542484 may impact the risk of epilepsy." (PMID 35801810, 2022). "So far, over 1100 pathogenic and likely pathogenic (PLP) variants for epilepsy, seizures, and hemiplegic migraines in SCN1A have been reported, with most of them located in the C-terminus and pore loops and the majority of variants identified in patients with SMEI." (PMID 35627139, 2022). "Variants in the gene SCN1A encoding Nav1.1 α subunit have been associated with a spectrum of epilepsy disorders ranging from the relatively benign generalized epilepsy with febrile seizures plus (GEFS+) to the devastating disorder, severe myoclonic epilepsy of infancy (SMEI)." (PMID 35359575, 2022). "Confirmation of the pathogenicity of the SCN1A variant is important to determine the recurrence risk for the family given the presence of mosaicism in the father and to direct future choices of medication therapy for epilepsy." (PMID 36229510, 2022). "By comparison, the response to LEV was inferior in PRRT2- and KCNQ2-related epilepsy, and it may probably be useful for SCN1A-associated epilepsy." (PMID 35720076, 2022).